U2 (U2 spliceosomal RNA )
Synonyms: LOC124905166
Gene: Small nuclear RNA gene on chromosome 22 (10,736,171 to 10,736,283, reverse strand). Ensembl gene ENSG00000277248.
Gene Ontology:
Molecular function: pre-mRNA branch point binding
Biological process: mRNA branch site recognition
Cellular component: U2 snRNP
Homologues: Orthologues: chimpanzee U2 (99% identical), macaque U2 (68% identical), guinea pig U2 (59% identical), dog U2 (58% identical), guinea pig U2 (58% identical), mouse Gm23788 (54% identical), pig U2 (53% identical), guinea pig U2 (52% identical), tropical clawed frog U2 (50% identical), dog U2 (48% identical), tropical clawed frog U2 (44% identical), rabbit U2 (42% identical). Paralogues in human: RNU2-42P (99% identical), U2 (98% identical), RNU2-6P (65% identical), RNU2-3P (65% identical), U2 (65% identical), RNU2-2 (64% identical), RNU2-4P (64% identical), RNU2-26P (63% identical), RNU2-57P (63% identical), RNU2-59P (63% identical), RNU2-32P (62% identical), RNU2-36P (62% identical), and 66 more.